SOX2 (SRY-box transcription factor 2)
Diseases named in the same sentence as SOX2 in open-access papers (continued):
Sharing a sentence is not in itself a finding about the gene and the disease.
breast cancer (continued). "As for the various molecular typing groups, low FOXO3a expression, or high expression of FOXM1, SOX2, and DNMT1 was relevant to shorter survival in ERα+ breast cancer patients." (PMID 31296961, 2020). "We further analyzed the correlation of Snail with Sox2, VEGF, and MVD in breast cancer patients by IHC." (PMID 32541667, 2020). "Taken together, these findings indicated that dysregulated FOXO3a/FOXM1/SOX2/DNMT1 signaling plays a critical role in disease progression and is a valuable biomarker in breast cancer." (PMID 31296961, 2020). "Accordingly, Sox2 positivity is rare in luminal-A (ER+, PR+, low Ki-67) breast cancers, and more common in triple-negative (ER–, PR–, HER2–) breast cancers." (PMID 33553286, 2020). "We demonstrate that betavulgarin suppresses the proliferation of breast cancer and BCSC formation through the regulation of Stat3/Sox2 signaling in BCSCs." (PMID 32630026, 2020). "We next analyzed the correlation of FOXO3a, FOXM1, SOX2, and DNMT1 expression to the prognosis of breast cancer patients with lymph node metastasis status." (PMID 31296961, 2020). "For example, in CRC, SOX2 plays a cancer-promoting role through METTL3-catalyzed methylation, while in breast cancer, BNIP3 plays a cancer-promoting role through FTO-catalyzed demethylation." (PMID 32398132, 2020). "CCAT1 increased expression of the stemness markers NANOG, SOX2, OCT4 and ALDH1A1, and promoted proliferation, invasion, and migration in the breast cancer cells." (PMID 32244924, 2020). "Here, we assessed the adhesion behavior of Sox2-expressing cells and parental MCF7 breast cancer cells at the single cell level using AFM and fluorescence microscopy." (PMID 32290242, 2020). "For example, upregulation of SOX2 activated PVT1 expression and accelerated the progression of breast cancer." (PMID 32549756, 2020). "In the current study, we found that DNMT1-mediated FOXO3a promoter hypermethylation leads to downregulation of FOXO3a expression in breast cancer, and FOXO3a suppresses BCSC properties and tumorigenicity via inhibition of FOXM1/SOX2 signaling." (PMID 31296961, 2020). "Next, we analyzed the clinicopathological implication of FOXO3a, FOXM1, SOX2, and DNMT1 levels in breast cancer patients." (PMID 31296961, 2020). "FACS analysis showed significantly increased levels of OCT4- (26.5-fold, p ≤ 0.001) in HCC70 and SOX2 (4.3-fold, p ≤ 0.01) -positive population of HCC1806 cells in NIC-treated breast cancer cells incubated with SAT compared to the cells plus SAT group." (PMID 33414685, 2020). "6-Methoxymellein inhibits the proliferation, migration, and colony and mammosphere formation of breast cancer cells and decreases the subpopulation of CD44+/CD24− and the expression of c-Myc, Sox-2 and Oct4 proteins." (PMID 32977636, 2020). "Thus, Sox2-enriched mammary carcinomas may be prone to immune-suppressed tumor microenvironments." (PMID 33553286, 2020). "Human tissues used for positive controls demonstrated positive staining of OCT4 and NANOG on sections of seminoma, SOX2 on skin, KLF4 on breast carcinoma, and c-MYC on colon." (PMID 32850316, 2020). "Positive controls demonstrated the expected staining pattern for OCT4 and NANOG in seminoma, SOX2 in normal skin, KLF4 in breast carcinoma, and c-MYC in normal colon." (PMID 32019273, 2020). "Human tissues for positive controls showed the expected staining patterns: for OCT4 and NANOG on seminoma, SOX2 on skin, KLF4 on breast carcinoma, and c-MYC on colon." (PMID 32850316, 2020). "In breast cancer-initiating stem cells, when stimulated by VEGF, VEGFR2 binds to JAK2 and activates STAT3, and maintains cell self-renewal by promoting MYC and SOX2 expression and induces sphere formation." (PMID 30819137, 2019). "In this study, we identified a novel mechanism of tamoxifen resistance in ER+ breast cancer cells through stabilization of TARBP2 protein and upregulation of SOX2." (PMID 30759864, 2019).
breast cancer (continued). "Elevated expression of SOX2 was reported to activate expression of the lncRNA PVT1, leading to breast cancer tumorigenesis." (PMID 31462898, 2019). "Pyrvinium pamoate, an anthelmintic drug and inhibitor of the Wnt/β-catenin pathway, prevented the proliferation of breast cancer cells, especially CD44+CD24−/low and ALDH+ CSCs, via downregulating NANOG, OCT4, and SOX2." (PMID 31137841, 2019). "Regarding breast cancer, Zhou and team showed that miR-590-5p inhibited BC cells stemness through targeting SOX2 and they suggested that miR-590-5p might be a useful strategy for BC treatment." (PMID 30842790, 2019). "Collectively, these results show that Rac1 is required for SOX2- and NEDD9-mediated breast cancer cell migration under hypoxia." (PMID 31462898, 2019). "They down-regulated Maspin and SOX2 expression in SUM159 and MCF-7 breast cancer cell lines using a synthetic epigenetic construct of six ZF domain (6ZF) array linked to the DNMT3a catalytic domain (6ZF-DNMT3a)." (PMID 31597272, 2019). "Among the most amplified genes, we find the oncogenes SOX2, EGFR, and MDM2, and also a noncoding gene, PVT1, the most amplified gene in breast cancer, with proven but as-of-yet uncharacterized proto-oncogenic effects." (PMID 31379928, 2019). "In further investigations, we identified a novel link between SOX2 and NEDD9 in the regulation of breast cancer cell migration under hypoxia." (PMID 31462898, 2019). "We also transfected breast cancer cells with specific siRNA for SOX2, NEDD9 or the Rac1 inactive mutant (T17 N) to investigate the role of SOX2, NEDD9 and Rac1 in the response to hypoxia." (PMID 31462898, 2019). "In agreement with our findings that SOX2 is a downstream of TARBP2 that modulates tamoxifen resistance, we also observed that SOX2 expression is correlated with poor prognosis of ER+ breast cancer patients." (PMID 30759864, 2019). "Recently, binding sites for OCT4, NANOG, SOX2 and SIN3A in breast cancer CTC clusters were shown to be hypomethylated to what is seen in embryonic stem cell biology." (PMID 30875950, 2019). "Here the authors show that TRIB3 enhances breast cancer stemness through interaction with AKT to promote FOXO1 stability, which then increases SOX2 activity." (PMID 31844113, 2019). "In mammary tumor cell lines downregulation of CD44 reduced and overexpression of CD44-ICD enhanced the expression of the stemness factors Nanog, Sox2 and Oct4." (PMID 30540779, 2018). "In breast cancer, Notch-ICD transactivates SOX2, which increases sphere formation, and expansion of ALDH1+ and CD44+ cells." (PMID 30211160, 2018). "LINC00617 in breast cancer regulates EMT, cancer progression, and metastasis through activation of the transcription of SOX2." (PMID 29757368, 2018). "For example, in breast cancer, PVT1 is significantly upregulated, and directly interacts with SOX2 to drive EMT." (PMID 29701689, 2018). "Many of the genes regulated have previously been shown to correlate with aggressiveness of breast cancer such as CD24, SOX2, Slug, Twist1, CD-133, N-Cadherin, E-Cadherin, FOXC2, ABCG2, c-Myc, IL8, IL6, and IKKβ (activating NF-κB signaling)." (PMID 29552303, 2018). "For example, SOX2 activated lncRNA ANRIL and PVT1 by binding their promoters in nasopharyngeal carcinoma and breast cancer, respectively." (PMID 30108202, 2018). "The results showed that SOX2 was strongly expressed in all 8 breast cancer cell lines, particularly in TNBC cell lines: The SOX2 expression levels for some of the TNBC, NTNBC or normal mammary cell lines." (PMID 30186173, 2018). "Previous studies have demonstrated that SNAI2 increases stemness in breast cancer cells when co-expressed with SOX9 or through regulation of stem cell markers, including c-Myc, SOX2 and Oct4, possibly contributing to drug resistance." (PMID 29921289, 2018).
breast cancer (continued). "Here, we inserted the four stem cell transcription factor genes OCT4, SOX2, C-MYC and KLF4 into MCF cells (MCFs), represented a female breast cancer cell type, and obtained iPSCs (Mcfips) in about 3 weeks." (PMID 28423718, 2017). "Expression of stemness-related genes including SOX2 and NANOG confirmed that mammosphere-forming culture of breast cancer cells enriched BCSC-like cells." (PMID 28703799, 2017). "Consistently, H19 expression was detected at higher levels in breast cancer cells than in breast epithelial cells and stemness-related factors OCT4, SOX2 and NANOG were expressed at higher levels in MDA-MB-231 cells compared with MCF-10A cells." (PMID 28102845, 2017). "Spearman’s rank order correlation coefficients of relative gene expression values for SOX2, AXIN2, and DKK1 in breast cancer samples from The Cancer Genome Atlas (TCGA_BRCA_exp_HiSeqV2-2015-02-24) data set (n = 1,009), *p < 0.05." (PMID 28929082, 2017). "Upregulation of SOX2 can activate PVT1 expression in breast cancer cells via binding to its promoter and promote breast cancer cell growth and invasion." (PMID 29244840, 2017). "Similar results were seen in breast cancer cell lines, as stable overexpression of SOX2 in MCF-7 cells promoted resistance to tamoxifen, while stable downregulation of SOX2 using shRNAs enhanced the sensitivity of MCF-7 cells to tamoxifen." (PMID 28388544, 2017). "A previous study using a MCF7 breast cancer cell line to produce MCF7-derived tumour xenografts found that P63 and SOX2 immunostainings were two potential markers for breast cancer." (PMID 29527291, 2017). "Among aggressive breast cancers expressing high VEGFA, those with SOX2 overexpression define an even more aggressive subgroup in the two independent data sets evaluated." (PMID 28504716, 2017). "H Li reported that LncRNA 00617 was highly expressed in breast cancer tissues and can promote the invasion and EMT in breast cancer cells by activating the transcription of SOX2." (PMID 28245841, 2017). "Similar to SOX2 and SOX2-OT, expression of SOX1-OT and SOX1 in breast cancer cell lines (MCF7 and T47D) also suggests a possible co-regulatory role in breast cancer." (PMID 28674729, 2017). "Positive controls were human seminoma for OCT4 (pink, arrows), normal skin for SOX2 (pink, arrows), seminoma for NANOG (pink, arrows), breast cancer for KLF4 (pink, arrows), and normal prostate for c-Myc (pink, arrows)." (PMID 29404335, 2017). "Inducibly elevating SOX2 (~5 to 7-fold) in glioblastoma (U87, U118), medulloblastoma (DAOY), breast carcinoma (MDA-MB-231), and prostate carcinoma (DU145) cell lines led to growth inhibition in each case." (PMID 28388544, 2017). "Given the pivotal role for Sox2 in stem cell self-renewal, BCSLC development and breast cancer outcomes, AHR/Sox2-specific ChIP assays were performed to determine if the AHR directly interacts with the Sox2 promoter." (PMID 26984638, 2016). "In the present study, hypoxia induced the HIF-dependent enrichment of BCSCs in all breast cancer cell lines, which was accompanied by increased expression of one or more pluripotency factors (NANOG, KLF4, or SOX2)." (PMID 27590511, 2016). "In recent studies, we found that hypoxia-inducible factors (HIFs) mediated increased NANOG, SOX2, and OCT4 expression in human breast cancer cells in response to chemotherapy or hypoxia." (PMID 27590511, 2016). "To clarify how KDM2A enhances stem-like properties of breast cancer cells, we investigated the alteration of stemness markers after KDM2A depletion and identified SOX2 as a key mediator." (PMID 27029061, 2016). "In ER+ breast cancer cell lines, expression of SOX2OT is positively correlated with SOX2 expression level, albeit at lower levels." (PMID 26136768, 2015). "We identified an inverse relationship between miR-208a and let-7a in breast cancer specimens, and found that SOX2, β-catenin and LIN28 are highly expressed in patients with advanced breast cancer opposed to lesser grades." (PMID 26460550, 2015).
breast cancer (continued). "SOX2 has been identified as a target of miR-140, and in ER-α breast cancer cells, estrogen stimulation lowers miR-140 expression through ER-α binding to an ERE flanking the mir-140 promoter, thus increasing levels of SOX2." (PMID 26220712, 2015). "Contrary to the findings in MCF7 and ZR-75-1 cells, ectopic expression of G9a reduced Sox2 protein levels in MDA-MB-231 cells, an ER(-) breast cancer cell line, and in glioblastoma cells (U87-MG and T98-G)." (PMID 26492085, 2015). "We identified networks regulated by known cancer drivers such as GATA3 and FOXA1 (breast cancer), SOX17 and FOXA2 (endometrial cancer), and NFE2L2, SOX2, and TP63 (squamous cell lung cancer)." (PMID 25994056, 2015). "In studies reported by us, we found that the transcriptional activity of Sox2, detectable by the Sox2 regulatory factor-2 (SRR2) reporter, is found only in a small subset of cells in estrogen receptor-positive breast cancer cell lines and patient samples." (PMID 25868977, 2015). "When G9a lysine methyltransferase activity was chemically inhibited in the ER(+) breast cancer cell line MCF7, Sox2 protein levels were decreased." (PMID 26492085, 2015). "In this report we show that SOX2OT positively regulates SOX2 expression, and the ectopic expression of SOX2OT in the breast cancer cell line MDA-MB-231 reduces the proliferation rate and increases anchorage independent growth." (PMID 25006803, 2014). "We therefore examined the expression of SOX2 and SOX2OT in a series of tamoxifen-resistant MCF-7 breast cancer sub-lines that had been cultured for prolonged periods either in the absence of estrogen or in the presence of the antiestrogen tamoxifen." (PMID 25006803, 2014). "Having considered Oct-4, Sox-2 and CD44 expression data, we wished to determine the tumorsphere formation capacity with HER2-overexpressing breast cancer." (PMID 24297508, 2014). "We used chromatin immunoprecipitation and a human genome-wide promoter microarray (ChIP-chip) to determine the promoter occupancies of Sox2 in the MCF7 RU and RR breast cancer cell populations." (PMID 25380620, 2014). "A weak (r = 0.219) but highly significant (p = 2.23×10−13) correlation between expression of SOX2 and SOX2OT was found, emphasizing the potential importance of this signaling pathway in human breast cancer." (PMID 25006803, 2014). "To address this question, we compared SOX2 and SOX2OT expression in a large collection of breast cancer samples from TCGA." (PMID 25006803, 2014). "In the present study, we analyzed the expression profiles of the same panel of stemness genes belonging to the OCT3/SOX2/NANOG/KLF4 core circuitry and acting in regulating stem cell biologyin a representative sample of primary breast cancer tissue." (PMID 25127259, 2014). "We examined the dysregulation of the stem cell markers (Oct-4, Sox-2 and CD44) and the tumorsphere formation in HER2-overexpressing human breast cancer cell lines." (PMID 24297508, 2014). "KLF4 acts in concert with OCT4, SOX2, and NANOG in hESCs, but is downregulated in some breast cancer cells compared with normal mammary cells." (PMID 23596564, 2013). "The positive correlation of the co-expression of SOX2 and CCND1 with tumorigenesis has also been demonstrated in clinical breast cancer samples." (PMID 24355041, 2013). "Expression of key transcription factors Sox2, Oct4, Klf4 and c-Myc, were significantly up-regulated in the mammospheres isolated from SKBR3 breast cancer cells." (PMID 23341935, 2013). "In contrast to the previous report, we observed a notable reduction in cell number by light microscopy, 48 hours after SOX2 induction, in both MCF7 and MDA-231 breast cancer cells." (PMID 22937156, 2012). "In our studies, SOX2 was elevated from an inducible promoter in the total population of infected DU-145 prostate cancer, as well as MCF7 and MDA-231 breast cancer cells." (PMID 22937156, 2012). "In breast cancer, STAT3 activation via EGFR signaling promotes SOX2 expression." (PMID 41511366, 2026).
breast cancer (continued). "In MDA-MB-231 breast cancer cells, Oxamate decreased Sox2 and E-cadherin but did not affect Nanog or N-cadherin." (PMID 40565174, 2025). "Propofol could inhibit the capacity of breast cancer cell stemness and proliferation by upregulation FOXO3, which inhibited SOX2 expression transcriptionally." (PMID 39991565, 2025). "Consequently, overexpression of SOX2, YAP and TAZ was observed in the nuclear fractions of ALDH+ cells from mammary tumors." (PMID 39979255, 2025). "FOXO3A suppresses breast cancer stem cell properties and tumorigenicity via inhibition of FOXM1/SOX2 signaling, suggesting that FRMD8 may have an effect on breast cancer stem cells." (PMID 40213945, 2025). "In addition, the effects of the correlation between SOX2 and SOX9 expression in malignant tumors, such as lung cancer and breast cancer, have attracted attention." (PMID 39684417, 2024). "The increased expression of HIF-1 dependent S100A10 can form complexes and interact with histone demethylase KDM6A, ultimately being recruited to the OCT4 binding site to erase H3K27 trimethylation chromatin markers and promote transcription of NANOG, SOX2 and KLF4 in breast cancer." (PMID 38561775, 2024). "Through controlling miR-34a and subsequently SOX2, HOTAIR upregulation in CSCs isolated from breast cancer cells may be essential for maintaining self-renewal potential." (PMID 39170516, 2024). "The regulation of iron depletion by FTH1 can slow down the self-renewal of breast cancer stem cells, while silencing FTH1 in SKOV3 cells can promote the stemness of cervical cancer cells and the up-regulation of NANOG, SOX2, OCT4." (PMID 38025726, 2023). "Exploration of the mechanism revealed that when matrix stiffness was increased, TAZ dissociated from NANOG, promoting the transcription of SOX2 and OCT4, which in turn increased the proportion of BCSCs in the breast cancer and promoted the stemness phenotype of breast cancer." (PMID 37916166, 2023). "In breast cancer, TRIB3 supports cell stemness by regulation of SOX2 transcription." (PMID 37189176, 2023). "Hypoxia, through hypoxia-inducible factor (HIF), is known to induce a human Embryonic SC (hESC)-like transcriptional program, including the induced pluripotent stem cell (iPSC) inducers OCT4, NANOG, SOX2, KLF4, and cMYC, in various cancer cell lines, including breast cancer." (PMID 36982940, 2023). "Finally, we show an increase in the breast cancer stem cell population due to ERβ1 antagonist using both ALDEFLUORTM and SOX2/OCT4 response element (SORE6) reporters in SUM159 and MDA-MB-231 cell lines." (PMID 36982940, 2023). "Similarly in breast cancer, Hh signaling can be enhanced via expression of tetraspanin 8 and LncRNA-Hh, which increases the expression of OCT4, SOX2, and NANOG and leads to enhanced self-renewal and oncogenicity 50,51." (PMID 36118530, 2022). "In addition, in a breast cancer model, TAMs were noted to establish a paracrine EGFR/STAT3/Sox2 signaling pathway and increase Sox2, Oct4, Nanog, AbcG2, and Sca-1 gene expression." (PMID 35740975, 2022). "Similarly, upregulated lncRNA linc00617 can also promote breast cancer cell motility and EMT process by modulating the Sox2 [(sex-determining region Y)-box 2] gene expression." (PMID 36685962, 2022). "Further, expression of lncRNA SOX2OT modulates Sox2 in ER positive and negative breast cancer samples." (PMID 36685962, 2022). "This is interesting, as SOX2 transcription and SNAIL expression have been reported to be SOD2-sensitive, and SNAIL overexpression alone is sufficient to generate tumor-initiating breast cancer cells." (PMID 35326667, 2022).